BBLN (bublin coiled coil protein)
Description:
Essential for intermediate filament organization in intestinal cells, interacts with intermediate filament and regulates intestinal lumen morphology.
Synonyms: C9orf16; EST00098; Hero9; MGC4639; FLJ12823
Tractability: No criterion of Open Targets' tractability assessment is met for any kind of drug.
Gene: Protein-coding gene on chromosome 9 (128,160,265 to 128,163,924, forward strand). Ensembl gene ENSG00000171159.
Subcellular location: Cell junction; Cytoplasm, cytoskeleton
Subcellular location (Human Protein Atlas): Microtubules
Gene Ontology:
Molecular function: molecular adaptor activity; protein binding
Biological process: intermediate filament bundle assembly
Cellular component: anchoring junction; cell junction; intermediate filament; kinetochore microtubule; subapical part of cell; cytoskeleton
Genetic constraint (gnomAD): Loss-of-function variants: 5 observed, 4.73 expected, observed/expected ratio (o/e) 1.06, 90% interval 0.54 to 1.84. That is too few expected variants to judge how well the gene tolerates losing a copy. Missense variants: 95 observed, 86.65 expected, observed/expected ratio (o/e) 1.1, 90% interval 0.93 to 1.3. Synonymous variants: 33 observed, 35.26 expected, observed/expected ratio (o/e) 0.94, 90% interval 0.71 to 1.25.
Homologues: Orthologues: chimpanzee BBLN (100% identical), macaque BBLN (100% identical), dog BBLN (96% identical), mouse Bbln (94% identical), guinea pig BBLN (89% identical), zebrafish bbln (57% identical), tropical clawed frog bbln (55% identical).
Diseases named in the same sentence as BBLN in open-access papers:
BBLN is named in the same sentence as 23 diseases in open-access papers, as found by Europe PMC text mining. Sharing a sentence is not in itself a finding about the gene and the disease. The quoted sentences say what the papers report.
ischemic stroke (2 papers, 2024 to 2025). A stroke disorder caused by obstruction of blood flow to the brain, due to thrombotic (local blood clot formation) or embolic (due to a blood clot or other material traveling from another site) event. "In order to address the involvement of Hero-proteins in the pathobiology of CVDs, we have previously conducted a genetic study exploring the associations of the genes C19orf53, SERBP1, SERF2, and C9orf16 (BBLN) with ischemic stroke." (PMID 40459864, 2025).
metastatic cancer (2 papers, 2022 to 2025). A carcinoma which has spread from the original site of growth to another anatomic site. "For instance, increased expression of C9orf16 (BBLN) was observed in primary and metastatic cancer cells of pancreatic ductal adenocarcinoma (PDAC) cells, a significant role of this gene in ovarian cancer progression was noted." (PMID 40459864, 2025).
cardiac hypertrophy (1 paper, 2023). "Taken together, our data strongly suggest that BBLN triggered cardiac dysfunction and cardiac hypertrophy by CAMK2D activation." (PMID 38666071, 2023). "Moreover, the inactive BBLN–SxxA mutant did not cause cardiac dysfunction and cardiac hypertrophy." (PMID 38666071, 2023).
Cyanosis (1 paper, 2023). Bluish discoloration of the skin and mucosa due to poor circulation or inadequate oxygenation of arterial or capillary blood. "Here, searching for pathomechanisms, we find upregulated bublin coiled-coil protein (BBLN) in heart specimens of TOF patients with cyanosis, which positively correlates with cardiac remodeling pathways." (PMID 38666071, 2023). "BBLN expression correlated with markers of adverse cardiac remodeling in right ventricular TOF patient heart specimens with cyanosis and in right ventricular heart tissue of Tg-BBLN mice." (PMID 38666071, 2023). "Immunohistological analyses found that BBLN protein contents were increased sixfold (range 1.9- to 11.45-fold) on cardiac biopsy specimens of TOF patients with cyanosis compared with those of acyanotic TOF cases." (PMID 38666071, 2023). "Whole-transcriptome analysis found that about 60% of transcripts, which positively correlated with BBLN levels in TOF patient heart specimens with cyanosis (874 transcripts), also showed upregulation in the right ventricles of Tg-BBLN mice." (PMID 38666071, 2023). "As in TOF patient heart specimens with cyanosis, Nppb was also upregulated in right ventricular heart specimens of Tg-BBLN mice." (PMID 38666071, 2023). "We found that BBLN was upregulated in human heart specimens of TOF patients with cyanosis." (PMID 38666071, 2023). "The overrepresentation analysis of transcripts having positive correlation with BBLN levels in right heart specimens of TOF patients with cyanosis and showing upregulation in right ventricles of Tg-BBLN mice documented that BBLN triggered major biological pathways involved in heart remodeling." (PMID 38666071, 2023). "To investigate the relationship between increased cardiac BBLN contents and TOF-related gene expression, we performed a whole-transcriptome analysis of RVOT specimens from TOF patients with cyanosis and right ventricular heart specimens from Tg-BBLN mice." (PMID 38666071, 2023). "Likewise, BBLN as a CAMK2D enhancer, triggered the immune system pathway, with prominent upregulation of heart failure-enhancing transcripts in Tg-BBLN mice and TOF patient heart specimens with cyanosis." (PMID 38666071, 2023). "The transcriptome analysis also found that 114 transcripts showed negative correlation with BBLN in TOF patients with cyanosis and downregulation in right ventricular heart specimens of Tg-BBLN mice." (PMID 38666071, 2023). "The positive correlation of a transcript with cardiac BBLN transcript levels in TOF patient heart specimens is exemplified for the heart failure and myocardial ischemia marker, natriuretic peptide type b (NPPB), which could be induced in TOF patients with cyanosis by the low oxygen condition." (PMID 38666071, 2023).
heart failure (1 paper, 2023). Inability of the heart to pump blood at an adequate rate to meet tissue metabolic requirements. "The upregulated BBLN protein, at least in the mouse model, promotes adverse cardiac remodeling and predisposes to an increased heart failure risk." (PMID 38666071, 2023). "Thus, moderately elevated cardiac BBLN levels are sufficient to cause fibrotic cardiac remodeling and features of heart failure." (PMID 38666071, 2023). "Echocardiographic analyses confirmed the immunohistological assessment and showed that the heart failure phenotype of Tg-BBLN mice was accompanied by enlargement of the left cardiac ventricles." (PMID 38666071, 2023). "The transcript intensity heat map documents the predominant upregulation of the heart failure-enhancing transcripts in right ventricles of Tg-BBLN mice compared with left cardiac ventricles." (PMID 38666071, 2023). "Tg-BBLN mice with 50.4 ± 8.2-fold increased cardiac BBLN protein levels (Tg-1), had an early heart failure phenotype with a strongly reduced left ventricular ejection fraction (EF) of 18.0 ± 6.0% and an increased mortality starting at an age of 3 months." (PMID 38666071, 2023). "The heart failure phenotype with an increased mortality was also observed in female Tg-BBLN mice." (PMID 38666071, 2023). "Human BBLN, a protein with largely unknown function, promoted heart failure features, with increased mortality when overexpressed in mice, in a protein dosage-dependent manner." (PMID 38666071, 2023). "Downregulation of CAMK2D by an interfering RNA retarded BBLN-induced symptoms of heart failure." (PMID 38666071, 2023). "However, increased BBLN contents in cardiac specimens of TOF patients were a consequence and not a cause of TOF defects because Tg-BBLN mice with heart failure had no septal defect." (PMID 38666071, 2023). "Although the human and murine BBLN amino acid sequences have 94% identity, the murine Bbln gene lacks the Egr1 consensus site and could therefore be upregulated by other modalities in different heart failure models." (PMID 38666071, 2023). "Tg-BBLN mice with signs of heart failure and calcium accumulation also showed DES fragmentation, in contrast, the DES protein was largely intact in transgenic Tg-BBLN–SxxA mice with expression of the inactive BBLN–SxxA mutant." (PMID 38666071, 2023). "These pathologically elevated endogenous cardiac BBLN protein levels contributed to cardiac dysfunction and necroptotic cardiac remodeling in vivo, in the AAC-induced heart failure model." (PMID 38666071, 2023). "Of those BBLN dependently upregulated cardiac transcripts of the ‘immune system’ pathway of TOF patients and Tg-BBLN mice, 23.8% have a documented pathological relevance for cardiac inflammation, cardiac remodeling and/or heart failure." (PMID 38666071, 2023).
osteoarthritis (1 paper, 2025). A noninflammatory degenerative joint disease occurring chiefly in older persons, characterized by degeneration of the articular cartilage, hypertrophy of bone at the margins and changes in the synovial membrane. "C9orf16 (BBLN) has been significantly regulated in synovitis of osteoarthritis, osteoporosis through its influence on bone mineral density." (PMID 40459864, 2025).
BBLN also shares sentences with these, for which no sentence is quoted: cancer (2 papers); ovarian carcinoma (2); Arrhythmia (1); cardiovascular diseases (1); colorectal cancer (1); dyslipidemia (1); hepatocellular carcinoma (1); high blood pressure (1); infection (1); lung carcinoma (1); Obesity (1); oral carcinoma (1); osteoporosis (1); pancreatic cancer (1); pancreatic ductal adenocarcinoma (1); Tetralogy of Fallot (1); tumor (1).